BTNL9 (butyrophilin like 9)
Synonyms: FLJ32535; BTN8; BTN3; VDLS1900
Tractability: Antibody: its Gene Ontology location is reachable by antibodies, with high confidence; UniProt predicts a signal peptide or a membrane-spanning region.
Gene: Protein-coding gene on chromosome 5 (181,040,225 to 181,061,524, forward strand). Ensembl gene ENSG00000165810.
Subcellular location: Membrane
Subcellular location (Human Protein Atlas): Nuclear membrane; Vesicles
Pathways (Reactome):
Immune System: Butyrophilin (BTN) family interactions
Gene Ontology:
Molecular function: signaling receptor binding
Biological process: regulation of cytokine production; T cell receptor signaling pathway
Cellular component: external side of plasma membrane; plasma membrane; membrane
Genetic constraint (gnomAD): Loss-of-function variants: 45 observed, 43.54 expected, observed/expected ratio (o/e) 1.03, 90% interval 0.81 to 1.33. The upper end of that interval is the gene's LOEUF score, 1.33, which puts it in group 5 of 6, group 1 being the genes least tolerant of losing a copy. Missense variants: 779 observed, 686.31 expected, observed/expected ratio (o/e) 1.14, 90% interval 1.07 to 1.2. Synonymous variants: 345 observed, 305.75 expected, observed/expected ratio (o/e) 1.13, 90% interval 1.03 to 1.23.
Homologues: Orthologues: chimpanzee BTNL9 (96% identical), macaque BTNL9 (89% identical), macaque BTNL9 (79% identical), dog BTNL9 (73% identical), rabbit BTNL9 (69% identical), pig BTNL9 (69% identical), mouse Btnl9 (69% identical), rat Btnl9 (69% identical). Paralogues in human: BTN3A3 (39% identical), BTN1A1 (38% identical), BTN2A1 (38% identical), BTN3A1 (37% identical), BTN2A2 (37% identical), BTNL3 (32% identical), BTNL8 (32% identical), ERMAP (30% identical), BTNL2 (23% identical), BTN3A2 (21% identical), CD276 (15% identical), MOG (13% identical), and 3 more.
Diseases named in the same sentence as BTNL9 in open-access papers:
BTNL9 is named in the same sentence as 45 diseases in open-access papers, as found by Europe PMC text mining. Sharing a sentence is not in itself a finding about the gene and the disease. The quoted sentences say what the papers report.
breast carcinoma (8 papers, 2019 to 2023). "Studies have identified a downregulation of BTNL9 expression in osteosarcoma, colon cancer, lung adenocarcinoma, and breast cancer." (PMID 36253800, 2022). "The findings showed that BTNL9 expression level was significantly lower in breast cancer, one colon cancer cohort, lung cancer, kidney cancer, and crabtree uterus cancer than normal tissues." (PMID 34635082, 2021). "A more recent study on breast cancer, involving a multiomics approach, also showed that higher mRNA levels of BTNL9 and of other family members in the BTN/BTNL family were associated with a more favourable DFS and extended OS." (PMID 35008260, 2021). "The lower expression of BTNL9 in breast cancer was significantly correlated with a worse DFS and OS." (PMID 35008260, 2021). "Later, by studying breast cancer cell lines they demonstrated that BTNL9 might have an anti-cancer role in breast cancer by inhibiting proliferation and metastasis." (PMID 35008260, 2021). "In addition, in a recent study, researchers took advantage of the TCGA database and verified that the expression of BTNL9 was downregulated in breast cancer." (PMID 35008260, 2021). "BTNL2, BTNL3, BTNL8, BTNL9, and SKINTL constitute the BTNL family, which regard as a tumor inhibitor in many cancers, such as malignant melanoma and breast cancer." (PMID 36034784, 2022). "Finally, 6 upregulated DEGs (CST2, DRP2, CLEC5A, SCD, KIAA1211, DTL) and 6 downregulated DEGs (STAC2, BTNL9, CA4, CD300LG, GPIHBP1 and PIGR), were confirmed in a quantitative real time PCR comparison of breast cancer and paracancerous breast tissues from 8 clinical specimens." (PMID 31182966, 2019).
colon cancer (4 papers, 2016 to 2023). "Specifically, a study discovered that patients with colon cancer had a worse prognosis when their blood levels of BTNL9 were greater, and IRX4 may play important roles in the development and progression of gastric cancer." (PMID 37359510, 2023).
lung adenocarcinoma (3 papers, 2017 to 2022). A carcinoma that arises from the lung and is characterized by the presence of malignant glandular epithelial cells. "Survival curve analysis revealed that lung adenocarcinoma patients with high expression of ZDHHC9, BTNL9, GNG11 or CPED1 are correlated with better survival outcomes." (PMID 29285217, 2017). "The mRNA expression of BTNL9, GNG11, or CPED1 is downregulated in lung adenocarcinoma when compared to normal tissue, and ZDHHC9 is upregulated." (PMID 29285217, 2017). "The analysis of the effects from each gene expression on survival outcome indicated that 6 genes (AGR2, SPDEF, CDKN2A, CLDN3, SFN, and PHLDA2) play oncogenic roles, and 7 genes (PDK4, FMO2, CPED1, GNG11, IL33, BTNL9, and FABP4) act as tumor suppressors in lung adenocarcinoma." (PMID 29285217, 2017). "However, since the genetic interactions of hsa-miR-183-5p-BTNL9, hsa-miR-33b-5p-CPED1, hsa-miR-429-CPED1, hsa-miR-182-5p-FMO2, hsa-miR-130b-5p-IL33, and hsa-miR-542-3p-IL33 have not been identified, these altered genetic regulations may play important roles in the progression of lung adenocarcinoma." (PMID 29285217, 2017).
breast tumor (1 paper, 2021). "The adaptive immune checkpoints BTNL9 and VTCN1 and the innate immune checkpoints CD200 and SIRPA were downregulated in breast tumor tissues while the metabolic immune checkpoints ADORA2A and TDO2 were upregulated in breast tumor tissues." (PMID 33932112, 2021).
cavernous hemangioma (1 paper, 2022). A hemangioma characterized by the presence of cavernous vascular spaces. "The results suggested that: 1) the ligand-receptor interactions between CXCL12 and CXCR4 play a significant role in the immune responses in cavernous hemangiomas; and 2) the high expression of BTNL9 may cause checkpoint blockade in BTNL9+EC through the binding of BTNL9 to T-cells." (PMID 35865633, 2022).
CNS cancer (1 paper, 2021). "However, BTNL9 expression was significantly higher in the brain and CNS cancer, colorectal cancer, esophageal cancer, leukemia, and lymphoma, than in normal tissue." (PMID 34635082, 2021).
colon adenocarcinoma (1 paper, 2021). "In contrast, BTNL9 was significantly increased in Colon adenocarcinoma (COAD), Kidney Chromophobe (KICH), and Kidney renal clear cell carcinoma (KIRC) compared with normal tissues." (PMID 34635082, 2021).
inflammatory bowel disease (1 paper, 2025). A spectrum of small and large bowel inflammatory diseases of unknown etiology. "A stopgain mutation was found in BTNL9, a member of the butyrophilin family that plays a role in inflammatory bowel disease (IBD), and a novel frameshift mutation was found in VNN1, which affects the gut mucosal barrier." (PMID 40894167, 2025).
lymph node metastasis (1 paper, 2021).
lymphocytic thyroiditis (1 paper, 2023). "As for clinical parameters, lower BTNL9 expression was shown in tall cell histological type, unifocal neoplasms, R1 and R2 residual tumors, and lymphocytic thyroiditis compared with other subtypes." (PMID 37798795, 2023).
melanoma (1 paper, 2022). A malignant, usually aggressive tumor composed of atypical, neoplastic melanocytes. "It has been reported that BTNL8 may be important for co-stimulation of primary immune response in the periphery at sites of inflammation, and BTNL9 can inhibit cancer aggression in melanoma cells." (PMID 36034784, 2022). "Additionally, based on the enrichment analysis in the Reactome pathway, we found that BTN family genes, such as BTNL8 and BTNL9, which play a vital role in the immune signaling pathway, were also obviously upregulated by NCTD in Vem-resistant melanoma." (PMID 36034784, 2022).
papillary thyroid cancer (1 paper, 2023). "Gene enhancers of BTNL9 were identified by interrogating H3K27ac ChIP-seq and RNA-seq data of papillary thyroid cancer (PTC) and benign thyroid nodule (BTN) tissues." (PMID 37798795, 2023).
Parkinson disease (1 paper, 2021). A progressive degenerative disorder of the central nervous system characterized by loss of dopamine producing neurons in the substantia nigra and the presence of Lewy bodies in the substantia nigra and locus coeruleus. "On the other hand, the top 4 significantly enriched KEGGs pathways in the low BTNL9 expression group were pathways implicated in Parkinson’s disease, oxidative phosphorylation, DNA replication, and proteasome pathways." (PMID 34635082, 2021).
sarcoma (1 paper, 2024). A usually aggressive malignant neoplasm of the soft tissue or bone. "Notably, SD3 was enriched in the negative regulation of RIG‐I signalling with high expression of BTNL9 and TXNIP, indicating endogenous anti‐immune activation and an anti‐antigen presentation module in sarcoma." (PMID 39658531, 2024).
thyroid gland disorder (1 paper, 2023). A disease involving the thyroid gland. "It showed that BTNL9 expression was significantly associated with different clinical T stages, N stages, extrathyroidal extension, pathologic stages, histological types, primary neoplasm focus types, residual tumors, thyroid gland disorder history and disease progression in THCA patients." (PMID 37798795, 2023).
thyroid nodule (1 paper, 2023). A small circumscribed mass in the THYROID GLAND that can be of neoplastic growth or non-neoplastic abnormality. "Besides, high BTNL9 expression in THCA was found to be related with favorable PFI in THCA based on TCGA datasets, and comprehensive bioinformatics analysis was conducted, suggesting the potential value of BTNL9 in differential diagnosis of thyroid nodules and clinical prognosis." (PMID 37798795, 2023).
tumor (13 papers, 2017 to 2023). "Spearman’s correlation analysis of the correlation between expression of BTNL9 and tumor mutation burden (TMB) in the TCGA LUAD cohort showed that BTNL9 is significantly negatively correlated with TMB (P = 1.4E-9)." (PMID 34635082, 2021). "Low BTNL9 expression levels associated with low infiltration levels of naïve B cells, and DCs in the tumor microenvironment are unfavorable for OS in LUAD patients." (PMID 34635082, 2021). "Moreover, the correlation between BTNL9 and TILs showed that BTNL9 was significantly negatively correlated with tumor purity, and previous studies report that low tumor purity is associated with poor prognosis." (PMID 34635082, 2021). "The correlations between BTNL9 and these cytokines/chemokines indicated its involvement in tumor immunity process." (PMID 37798795, 2023). "Specifically, subgroup survival analysis showed that increased BTNL9 expression was associated with favorable RFS in female patients, tumor with low neoantigen load and patients with stage 1 THCA." (PMID 37798795, 2023). "It showed that in univariate model, pathologic stage, tumor extrathyroidal extension and BTNL9 expression were related to PFI." (PMID 37798795, 2023). "The expression levels of BTNL9 were significantly down-regulated in THCA samples compared to normal tissues, and were strongly associated with different tumor stages, immune cell infiltrations, chemokines/cytokines and immune checkpoint genes in THCA." (PMID 37798795, 2023). "The results implied an important role of BTNL9 in the tumor progression, with the possibility of serving as a novel prognostic biomarker and a potential therapeutic target for THCA." (PMID 37798795, 2023). "BTNL9 had a higher basal expression level, and its expression level in normal tissues was higher than that in tumor tissues." (PMID 36033440, 2022). "The activation of the RAS/MEK signaling pathway can downregulate BTNL9 expression, thereby deregulating BTNL9 inhibition of tumor cell invasion, leading to poorer prognostic outcomes." (PMID 36253800, 2022). "Analysis of the correlation between gene expression of BTNL9 and infiltrating level of immune cells using TIMER database showed that BTNL9 was negatively correlated with tumor purity (r = − 0.124, P = 5.6E-03)." (PMID 34635082, 2021). "Correlation between BTNL9 expression and tumor-infiltrating immune cells (TILs) was explored using TIMER and GEPIA databases." (PMID 34635082, 2021). "Genetic mutations are implicated in the tumor microenvironment (TME); therefore, the relationship between the expression of BTNL9 and the immune score was determined using the ESTIMATE algorithm in the SangerBox tool." (PMID 34635082, 2021). "The findings from this study provide information on the relationship between immune checkpoint BTNL9 and tumor immune response." (PMID 34635082, 2021). "Analysis showed that expression levels of BTNL8 and BTNL9 were significantly lower in tumor tissues compared with that of normal tissues." (PMID 34635082, 2021). "CD300LG and BTNL9, which exhibited more than 32-fold downregulation in all the tumor transcriptomes, showed a very high differential expression patterns." (PMID 31182966, 2019). "The expression level of CD300LG (2343 RPKM) and BTNL9 (7326 RPKM) were very high in normal tissues but very low in the tumor transcriptome (56 RPKM and 283 RPKM, respectively)." (PMID 31182966, 2019). "Previous studies show that high expression of NR4A2, BTNL9, FOXP1, or PDE4D can antagonize immune response or is associated with tumor progression." (PMID 30911684, 2019). "Two genes, PIGR and BTNL9, showed downregulation by 32-fold and 26-fold, respectively, in tumor tissues compared to normal tissues." (PMID 31182966, 2019). "Analyses of BTNL9 expression in different clinical and pathologic stages showed decreased expression in more advanced stages, indicating BTNL9 might participate in tumor progression." (PMID 37798795, 2023).
tumor (continued). "Although the function of BTNL9 in tumorigenesis remains unclear, our results suggest that BTNL9 may serve as a tumor suppressor." (PMID 29285217, 2017). "Furthermore, the functional enrichment analysis showed BTNL9 was involved in the immune-related and tumor-related regulating signaling pathways, indicating that low expression of BTNL9 might promote cancer development in THCA." (PMID 37798795, 2023). "BTNL9 is a member of Butyrophilin (BTN) and Butyrophilin-like (BTNL) families, involved in inflammatory diseases and tumor development through the regulation of the T cell response." (PMID 36253800, 2022). "Whereas, downregulated genes included GJA4, which is a component of gap junctions that are downregulated in CSCs, and BTNL9 and ITGA7, which are proposed tumour suppressors in breast." (PMID 34253873, 2021).
cancer (6 papers, 2018 to 2023). A tumor composed of atypical neoplastic, often pleomorphic cells that invade other tissues. "Another highly upregulated gene was found to be Butyrophilin-Like Protein 9 (BTNL9) which has been implicated to be of prognostic significance in various cancer types." (PMID 38090581, 2023). "The DEGs associated with BTNL9 were mainly involved in immune-related and cancer-related pathways." (PMID 37798795, 2023). "BTNL9 was reported to have lower expression levels in various cancers compared to normal tissues, including colon cancer, lung adenocarcinoma, osteosarcoma, breast cancer and uveal melanoma." (PMID 37798795, 2023). "While the roles of HSPD1 and KLRG2 play a role in regulating γδ T cell-mediated cytotoxicity in cancer have been described, there is limited information about the involvement of BTNL9 in γδ T cell-mediated killing of cancer cells." (PMID 38090581, 2023). "Functional enrichment analyses indicated that BTNL9 was involved in immune-related and cancer-related pathways." (PMID 37798795, 2023). "Findings showed that BTNL9 was significantly negatively correlated with cancer cell malignant behaviors such as proliferation, invasion, EMT, metastasis, and hypoxia." (PMID 34635082, 2021). "BTNL9 expression levels in other 32 types of cancer were analyzed with TCGA and GTEx datasets." (PMID 37798795, 2023). "Few studies reported the roles and mechanisms of BTNL9 in cancer." (PMID 37798795, 2023). "Besides from THCA, decreased expression levels of BTNL9 gene were also presented in various cancers according to TCGA datasets, which is consistent with previous studies." (PMID 37798795, 2023). "Butyrophilin-like protein 9 (BTNL9) is a member of the immunoglobulin butyrophilin and butyrophilin-like (BTNL) families, modulating the T cell response and impacting inflammatory disorders and cancers." (PMID 37798795, 2023). "Of the 201 downregulated genes, 125 were identified in the previous study (GEO results) and only 76, such as cysteine rich domain 2 (STAC2), BTNL9, CA4, GPIHBP1 and PIGR, had not been studied on any cancer." (PMID 31182966, 2019).
infection (2 papers, 2013 to 2025). The state of being infected such as from the introduction of a foreign agent such as serum, vaccine, antigenic substance or organism. "Case 6 has a sibling with PANS who also developed infection-induced catatonia, who has the TEP1, BTNL9 and VNN1 variants." (PMID 40894167, 2025).
BTNL9 also shares sentences with these, for which no sentence is quoted: Barrett esophagus (1 paper); bladder cancer (1); bladder tumor (1); Bladder Urothelial Carcinoma (1); cervical cancer (1); cholangiocarcinoma (1); colorectal cancer (1); dilated cardiomyopathy (1); esophageal cancer (1); gastric cancer (1); Glioblastoma multiforme (1); head and neck squamous cell carcinoma (1); immune disorders (1); kidney cancer (1); leprosy (1); leukemia (1); lung carcinoma (1); lymphoma (1); neurodevelopmental disorder (1); osteosarcoma (1); ovarian carcinoma (1); preeclampsia (1); Sepsis (1); thyroid cancer (1); ulcerative colitis (1); uterus cancer (1).